HMGB2 (high mobility group box 2)
Diseases named in the same sentence as HMGB2 in open-access papers (continued):
Sharing a sentence is not in itself a finding about the gene and the disease.
liver cancer (2 papers, 2024 to 2025). An epithelial or non-epithelial malignant neoplasm that arises from the liver. "Targeting HMGB2 inhibits liver cancer growth by bolstering CD8+ T cell function and inhibiting tumor cell growth." (PMID 40315321, 2025). "HMGB2 demonstrated heightened expression in all liver cancer cell lines except MHCC-97H." (PMID 39591457, 2024). "Given that HMGB2 has overlapping functional domains with HMGB1 and plays a certain role in the malignant progression of various tumors, this study speculates that HMGB2 also has a certain impact on the malignancy of liver cancer." (PMID 39591457, 2024).
Sepsis (2 papers, 2022 to 2025). Sepsis is defined as life-threatening organ dysfunction caused by a dysregulated host response to infection. "Among 5,607 DEGs, Lrg1, Ace2, Itgb6, Hmgb2, Pik3r5, Itgam, Plcb1, Jak2, Vegfa, and Hif1α were associated with the entire course of sepsis-induced myocardial injury, which have been reported previously." (PMID 35721566, 2022). "In conclusion, we used machine learning algorithms to identify 3 key DDR-related genes, GADD45A, HMGB2, and RPS27L, which exhibit a good diagnostic impact on sepsis." (PMID 39889168, 2025). "The calibration plots showed that the nomogram model composed of 3 genes, GADD45A, HMGB2, and RPS27L, exhibited good diagnostic prediction for sepsis." (PMID 39889168, 2025). "Importantly, we identified 3 pivotal genes, including GADD45A, HMGB2, and RPS27L, which exhibited good diagnostic prediction for sepsis." (PMID 39889168, 2025). "Three different expressed DDR-related genes (GADD45A, HMGB2, and RPS27L) were identified as sepsis biomarkers." (PMID 39889168, 2025).
acute liver failure (1 paper, 2026). Rapid deterioration of liver function causing encephalopathy and coagulopathy. "Finally, a significant correlation between Suv39h1, HMGB2 and proliferative markers was identified in patients with acute liver failure." (PMID 41963467, 2026).
acute lung injury (1 paper, 2022). A condition of lung damage that is characterized by bilateral pulmonary infiltrates (pulmonary edema) rich in neutrophils, and in the absence of clinical heart failure. "In experimental and clinical acute lung injury (ALI), the content of extracellular HMGB2 increases, which means that HMGB2 has a potential role in tissue injury." (PMID 35720285, 2022).
allergic rhinitis (1 paper, 2023). Inflammation of the nasal mucous membranes caused by an IgE-mediated response to external allergens. "This research aimed to explore the serum high-mobility group box 1 (HMGB1) and high-mobility group box 2 (HMGB2) levels in allergic rhinitis (AR) children and its correlation with clinical results." (PMID 37713866, 2023).
Allergy (1 paper, 2023). An allergy is an immune response or reaction to substances that are usually not harmful. "It was found that HMGB1, HMGB2, IL-6, IL-1β, and family history of allergy were the risk factors for AR." (PMID 37713866, 2023). "Finally, we found that HMGB1, HMGB2, IL-6, IL-1β, and family history of allergy were the risk factors for AR." (PMID 37713866, 2023).
aneurysm (1 paper, 2025). Bulging or ballooning in an area of an artery secondary to arterial wall weakening. "Elevated HMGB2 and HMGB1 levels were associated with higher risks of AAA (HMGB2: OR: 1.158, 95% CI: 1.011–1.325; p < 0.05; HMGB1: OR: 1.275, 95% CI: 1.048–1.551; p < 0.05) and aneurysm rupture (HMGB2: OR: 1.117, 95% CI: 1.005–1.241; p < 0.05; HMGB1: OR: 1.212, 95% CI: 1.003–1.465; p < 0.05)." (PMID 40776964, 2025).
astrocytomas (1 paper, 2024). "In grade 4 astrocytomas, HMGB2 expression was strongly associated with proliferative activity and microvascular proliferation." (PMID 38672598, 2024). "HMGB2 expression increased even before histological markers of evolution appeared in grades 2 and 3 astrocytomas, and it was associated with poor survival." (PMID 38672598, 2024). "To evaluate the prognostic potential of HMGB2 expression in grade 4 astrocytomas, we performed univariable and multivariable analyses in our validation cohort 2 to assess associations with OS." (PMID 38672598, 2024). "Grounded in proteomic findings, our results showed that HMGB2 expression assessed by IHC detected early signs of tumor progression in grades 2 and 3 astrocytomas, as well as identified GBMs and A4 IDHmut that had better response to the standard chemoradiation with temozolomide." (PMID 38672598, 2024). "Grounded in proteomic findings, our results showed that HMGB2 expression assessed by IHC detected early signs of tumor progression in grades 2 and 3 astrocytomas, as well as identified GBMs that had a better response to the standard chemoradiation with temozolomide." (PMID 38672598, 2024). "We validated our finding in multiplatform-omics studies and high-throughput IHC analysis, which raised several important hypotheses on the role of HMGB2 in astrocytoma progression and response to treatment, which are currently being investigated by our group." (PMID 38672598, 2024). "Taken together, these results suggest that HMGB2 expression is, at least in part, regulated by DNA methylation, and increases in grades 2 and 3 astrocytomas before the histological characteristics of grade 4 (necrosis and microvascular proliferation) are evident." (PMID 38672598, 2024). "Based on similarities between HMGB1 and HMGB2, we hypothesize that astrocytomas with high HMGB2 expression have a more powerful immune response to damage-associated molecular patterns (DAMPs), arising after RT plus temozolomide and/or oncolytic viral vectors injection." (PMID 38672598, 2024). "Therefore, HMGB2 may be an early predictor of a worse prognosis for grades 2 and 3 astrocytomas." (PMID 38672598, 2024).
Atrophy (1 paper, 2023). Any weakening or degeneration, especially through lack of use. "Moreover, HMGB2 is important for the development and maintenance of ovarian follicles in mice, as HMGB2 knockout results in ovarian atrophy and fibrosis." (PMID 37176041, 2023).
Autoimmunity (1 paper, 2022). The occurrence of an immune reaction against the organism's own cells or tissues. "The presence of serum anti-HMGB2 antibody contributes to inflammatory bowel disease, which indicates that extracellular HMGB2 plays a role in regulating autoimmunity." (PMID 35720285, 2022).
brain tumor (1 paper, 2024). "Notably, genes downregulated at P14, such as Kif11 and HMGB2, exhibited significant enrichment across all pediatric brain tumor groups, suggesting the importance of astrocytic gene repression during cerebellar development to these tumor subtypes." (PMID 38256095, 2024).
cerebral infarction (1 paper, 2022). An ischemic condition of the brain, producing a persistent focal neurological deficit in the area of distribution of the cerebral arteries. "In summary, the current study demonstrated that downregulation of HMGB2 decreased the infarct size, inflammatory responses, and apoptosis in cerebral injury and had neuroprotective effects against cerebral infarction-induced brain damage." (PMID 35966335, 2022). "In conclusion, the current study demonstrated that downregulation of HMGB2 decreased the infarct size, inflammatory responses, and apoptosis in cerebral injury and further had neuroprotective effects against cerebral infarction-induced brain damage." (PMID 35966335, 2022). "The functions of HMGB2 are widely reported in cardiovascular disease, but less research has been done in cerebral infarction." (PMID 35966335, 2022).
cerebral malaria (1 paper, 2022). A sequestration of Plasmodium falciparum in the brain, which can cause coma and/or seizures. "Studies in rodent malaria parasite P. yoelii have demonstrated a role for HMGB2 in mosquito infection while in P. berghei it acts as an alarmin contributing to the cerebral malaria and confers long-lasting protection in a murine experimental cerebral malaria." (PMID 36506024, 2022).
cyst (1 paper, 2022). A sac-like closed membranous structure that may be empty or contain fluid or amorphous material. "Therefore, we hypothesized that germ cell apoptosis may be elevated during cyst breakdown in HMGB2-KO mouse." (PMID 36539852, 2022).
diabetic retinopathy (1 paper, 2025). "Single-cell mRNA sequencing of retinal cells demonstrated that Cirbp, Mt1, Rbm3, Hmgb2, Mt2 are upregulated in mice with diabetic retinopathy in all retinal cells analyzed (rods, cones, Muller ̈ cells, retinal glia)." (PMID 40979707, 2025).
diffuse astrocytoma (1 paper, 2024). A low-grade (WHO grade II) astrocytic neoplasm. "Taken together, these results suggest that while HMGB2 may play a role in the progression of grades 2 and 3 diffuse gliomas, in fully developed grade 4 diffuse astrocytomas, higher HMGB2 expression may be a biomarker of treatment response." (PMID 38672598, 2024). "This justified further analyses of HMGB2 expression in diffuse astrocytomas." (PMID 38672598, 2024). "Interestingly, contrary to previous studies showing that high HMGB2 expression was related to treatment resistance in vitro, here, we observed significantly better survival in patients with grade 4 diffuse astrocytomas (GBM and A4 IDHmut) treated with adjuvant chemoradiation." (PMID 38672598, 2024).
endometrial cancer (1 paper, 2025). Primary or metastatic malignant neoplasm involving the endometrium (mucous membrane that lines the endometrial cavity). "HMGB2 knockdown significantly suppressed cancer cell proliferation, migration, and invasion across breast, cervical, ovarian, and endometrial cancer cell lines." (PMID 40396172, 2025). "HMGB2 knockdown in macrophages led to a significant impairment in phagocytosis of breast, cervical, ovarian, and endometrial cancer cells." (PMID 40396172, 2025). "In endometrial cancer cells, Ishikawa and RL95-2, HMGB2 knockdown caused a consistent decrease in proliferation." (PMID 40396172, 2025). "Our study provides compelling evidence that HMGB2 plays a critical role in regulating the proliferative, migratory, and invasive capacities of cancer cells in female-specific cancers, including breast, cervical, ovarian, and endometrial cancers." (PMID 40396172, 2025). "Endometrial cancer cells (Ishikawa and RL95-2) also showed a significant reduction in proliferation after HMGB2 knockdown and Palbociclib treatment." (PMID 40396172, 2025). "In endometrial cancer cell lines (Ishikawa and RL95-2), HMGB2 knockdown significantly impaired migration." (PMID 40396172, 2025). "In endometrial cancer cell lines (Ishikawa and RL95-2), HMGB2 knockdown significantly reduced cell invasion." (PMID 40396172, 2025).
epithelial ovarian cancer (1 paper, 2020). "Considering the relevance of HMGB proteins in Epithelial Ovary Cancer (EOC), we have determined for the first time the interactome of HMGB1 and HMGB2 related to this gynecological cancer." (PMID 32867128, 2020).
esophageal squamous cell carcinoma (1 paper, 2025). Esophageal squamous cell carcinoma (ESCC) is a type of esophageal carcinoma (EC) that can affect any part of the esophagus, but is usually located in the upper or middle third. "High mobility group box 2 (HMGB2), a chromatin-associated protein, is implicated in various cancers, yet its role in regulating NK cells, particularly in esophageal squamous cell carcinoma (ESCC), is unclear." (PMID 41280896, 2025). "In conclusion, this study identifies HMGB2 as a novel negative regulator of NK cell function in esophageal squamous cell carcinoma (ESCC)." (PMID 41280896, 2025).
HCMV infection (1 paper, 2019). "Compared to non-silencing (ns) control siRNA treated cultures, significantly less IFNB1 mRNA accumulated in response to HCMV infection upon HMGB2-depletion." (PMID 31841110, 2019).
Hydrocephalus (1 paper, 2017). Hydrocephalus is an active distension of the ventricular system of the brain resulting from inadequate passage of CSF from its point of production within the cerebral ventricles to its point of absorption into the systemic circulation. "Similarly, a large increase in adulthood-evident hydrocephalus/ventriculomegaly in the HMGB2-/- mouse brain may be indicative of mosaicism in cortical development due to the germline loss of this critical chromatin structural regulator." (PMID 28588451, 2017).
Hyperinsulinemia (1 paper, 2025). An increased concentration of insulin in the blood. "Mature human adipocytes undergo senescence under obesity and hyperinsulinemia stimulation, exhibiting premature aging transcriptomic and secretory characteristics, including upregulation of CDKN2A, CDKN1A, and CCND1 gene expression, and downregulation of HMGB1 and HMGB2 gene expression." (PMID 39963130, 2025).
ischemia (1 paper, 2022). A hypoperfusion of the BLOOD through an organ or tissue caused by a PATHOLOGIC CONSTRICTION or obstruction of its BLOOD VESSELS, or an absence of BLOOD CIRCULATION. "Finally, these results indicated that the downregulation of the TLR4/NF-κB pathway after ischemia by HMGB2 inhibition is a potential mechanism of the neuroprotective effect of cerebral injury." (PMID 35966335, 2022). "Finally, these results indicated that downregulation of the TLR4/NF-κB pathway after ischemia by HMGB2 inhibition was a potential mechanism for the neuroprotective effect of cerebral injury." (PMID 35966335, 2022).
nasopharyngeal carcinoma (1 paper, 2025). A carcinoma arising from the nasopharyngeal epithelium. "In nasopharyngeal carcinoma (NPC), the same family of HMGB2, high mobility group box 1 (HMGB1), the direct target of dead box helicase 5 (DDX5), is upregulated by the NAT10-mediated ac4C modification of DDX5, which inhibits the T-cell immunity of CD4 + and CD8 + T cells and promotes NPC progression." (PMID 41316475, 2025).
neuroblastoma (1 paper, 2025). Neuroblastoma (NB) is the most common solid, extracranial childhood tumor. "We next repeated the TDP-43 IP-qPCR assays in the nuclear extracts of SH-SY5Y neuroblastoma cells treated with MPP+ in triplicate and found that TDP-43 binding to MALAT1 was significantly increased, while TDP-43 binding to the 3′ UTR of SLC1A5, CSNK1E, and HMGB2 mRNAs was significantly decreased." (PMID 39837396, 2025).
ovarian tumor (1 paper, 2020). "In the library prepared from ovarian tumor tissue, 5 clones with coding sequences were identified using the HMGB1 bait (C1QA, DAG1, RPL29, RSF1, TGM2), and 6 (COMMD1, MIEN1, PCBP1, TBC1D25, ZFR, ZNF428) were identified with the HMGB2 bait." (PMID 32867128, 2020).
pancreatic adenocarcinoma (1 paper, 2020). "Using the GSE15471 and TCGA-Pancreatic adenocarcinoma (PAAD) datasets, we analyzed the clinical importance of TOP2A-associated genes (HDAC1, HDAC2, HMGB1, HMGB2, NFYA, NFYB, NFYC, and SP1)." (PMID 32977589, 2020).
pancreatitis (1 paper, 2024). Inflammation of the pancreas. "Among them, three genes (HMGB2, LDHA and AKT3) were reported to be closely related to pancreatitis, and no gene was reported to be associated with EBV infection." (PMID 39546499, 2024).
progeria (1 paper, 2022). "Interestingly, 6000 human genes were examined in aged and progeria people, and the results revealed that HMGB2 was one of 9 genes that were down-regulated." (PMID 36539852, 2022).
retinal degeneration (1 paper, 2024). Degeneration of the retina. "Vice versa, the knockdown of HMGB2 suppresses cell death in a light-induced retinal degeneration (LIRD) mouse model." (PMID 39389360, 2024).
rheumatoid arthritis (1 paper, 2014). A chronic, systemic autoimmune disorder characterized by inflammation in the synovial membranes and articular surfaces. "Early reports have demonstrated that antibodies to HMGB1 and HMGB2 are found in about 1/3 of SSc Sera and anti-HMGB1/HMGB2 antibodies are detected commonly in systemic rheumatic diseases, particularly in rheumatoid arthritis and SSc." (PMID 25284457, 2014).
small cell neuroendocrine carcinoma (1 paper, 2024). "The effects of HMGB1 and HMGB2 silencing upon the expression of genes previously related to PCa were studied in the PCa cell line PC-3 (selected as a small cell neuroendocrine carcinoma, SCNC, PCa model not responding to hormonal treatment)." (PMID 38542079, 2024).
squamous intraepithelial lesion (1 paper, 2021). "Most of high-grade squamous intraepithelial lesion tissues (HSIL) had weak nuclear stains for HMGB2." (PMID 33407071, 2021).